S100A7L2 (S100 calcium binding protein A7 like 2)
Synonyms: S100A7B
Gene: Unprocessed pseudogene on chromosome 1 (153,437,058 to 153,438,329, reverse strand). Ensembl gene ENSG00000197364.
Genetic constraint (gnomAD): Loss-of-function variants: 3 observed, 4.38 expected, observed/expected ratio (o/e) 0.69, 90% interval 0.31 to 1.63. That is too few expected variants to judge how well the gene tolerates losing a copy. Missense variants: 146 observed, 135.46 expected, observed/expected ratio (o/e) 1.08, 90% interval 0.94 to 1.24. Synonymous variants: 50 observed, 46.24 expected, observed/expected ratio (o/e) 1.08, 90% interval 0.86 to 1.37.
Diseases named in the same sentence as S100A7L2 in open-access papers:
S100A7L2 is named in the same sentence as 5 diseases in open-access papers, as found by Europe PMC text mining. Sharing a sentence is not in itself a finding about the gene and the disease. The quoted sentences say what the papers report.
lung adenocarcinoma (2 papers, 2022 to 2024). A carcinoma that arises from the lung and is characterized by the presence of malignant glandular epithelial cells. "We found CD1A|CXCL13, CD1A|S100A7L2, IFNA7|CMTM2, IFNA7|CSF3, CAMP|TFR2, this 5‐IRGPs were strongly associated with the prognosis of patients, all of which were protective factors for the prognosis of lung adenocarcinoma." (PMID 35246970, 2022).
cancer (3 papers, 2021 to 2023). A tumor composed of atypical neoplastic, often pleomorphic cells that invade other tissues.
tumor (1 paper, 2024). "S100A7L2 is also involved in cell migration and invasion, creating a proinflammatory and proangiogenic environment that promotes tumor progression and metastasis." (PMID 38791918, 2024). "PD-L1 high-expressing tumors show hypermethylated genes and promoters with strong oncogenic effects (SNORD114-14, DCAF4L2, S100A7L2, and SOD1P3) and hypermethylated genes and promoters with tumor suppressor effects (CELF2-AS1 and LINCMD1)." (PMID 38791918, 2024).
S100A7L2 also shares sentences with these, for which no sentence is quoted: lung carcinoma (1 paper); squamous carcinoma (1).